MDM2 (MDM2 proto-oncogene)
Diseases named in the same sentence as MDM2 in open-access papers (continued):
Sharing a sentence is not in itself a finding about the gene and the disease.
cancer (continued). "However, the relevance of the MYCN → MDM2 axis in developing tumors, as opposed to immortalized cancer cell lines, had not been demonstrated." (PMID 33425720, 2020). "Moreover, the carcinogenic role of USP7 in these types of cancer has been attributed to USP7-mediated deubiquitination and stabilization of MDM2 and MDMX, which has been validated by demonstrating the anticancer activity of USP7 inhibitors in vitro and in vivo." (PMID 32300595, 2020). "However, the role of MDM2 in cancer cells in the context of immunotherapy resistance remains not well-understood." (PMID 32655895, 2020). "Therefore, simultaneous inhibition of MDM2 and XIAP could serve as a powerful strategy to target cancer." (PMID 31310659, 2019). "Furthermore, the possible connection between USP15 and cancer progression came from the discovery that USP15 exerts its deubiquitinating activity to stabilize several proto-oncogene proteins, such as E3 ubiquitin ligase MDM2 and type I TGF-β receptor." (PMID 28245560, 2017). "Human MDM2, also referred to as human double minute 2 (HDM2), is located on chromosome 12q14.3–q15 and overexpression and/or amplification of MDM2 has been observed in various human cancers and can contribute to genomic instability, thus, further promoting tumorigenesis." (PMID 29065514, 2017). "Thus, the objective of this study was to synthesize compounds based computational modeling that indicated the pyrido[3,4-b]indole class bind to MDM2, a new cancer target for which there are still no drug on the market." (PMID 29354330, 2017). "In addition, RITA can promote down-regulation of MDMX selectively in wild-type cancer cells through a pathway independent of MDM2." (PMID 27187415, 2016).
cancer (continued). "We validate the gene activity score using data from the Cancer Cell Line Encyclopedia and drug sensitivity data for five compounds: BYL719 (PIK3CA inhibitor), PLX4720 (BRAF inhibitor), AZD6244 (MEK inhibitor), Erlotinib (EGFR inhibitor), and Nutlin-3 (MDM2 inhibitor)." (PMID 26864072, 2016). "In human cancers with Mdm2 gene amplification the negative effect of Mdm2 on TFII-driven transcription could disrupt normal cellular functions of TFII-I." (PMID 26656605, 2015). "Our studies including previous one identify the binding between the MDM2 RING domain and XIAP IRES RNA that simultaneously increases expression of XIAP and MDM2, which provides an excellent molecular target to develop an alternative/innovative strategy for cancer therapeutics." (PMID 25888903, 2015). "Interestingly, herein we found that knockdown of MDM2 was not able to induce death in G/G SNP309 cancer cells, suggesting the need to determine other targeted treatments for such MDM2 overexpressing cancers." (PMID 26416444, 2015). "Because binding of XIAP IRES to the MDM2 RING protein inhibited MDM2 homodimerization, which resulted in inhibition of MDM2 self-ubiquitination, we evaluated the cellular consequences of XIAP IRES-mediated inhibition of MDM2 self-ubiquitination in cancer cells." (PMID 25888903, 2015). "The HIV promoter was active in human cancer cells but did not respond to either TFII-I or Mdm2." (PMID 26656605, 2015). "These insights identify MDM2 and ATRX as new regulators controlling geroconversion, the process by which quiescent cells become senescent, and this insight may be exploited to improve the activity of CDK4i in cancer therapy." (PMID 25803170, 2015). "Therefore, drugs targeting DNMT protein inactivation and depletion, such as MDM2, AKT and CDKs inhibitors may prove to be a good therapeutic strategy for cancer treatment." (PMID 25949795, 2014).
cancer (continued). "Interestingly, MDM2 inhibitors have been reported to induce cancer cell apoptosis even without the concomitant application of genotoxic stimuli." (PMID 23977270, 2013). "Therefore, although Arf is a known regulator of Mdm2, Arf levels do not appear to regulate Mdm2 in non-oncogene driven cancers." (PMID 23029416, 2012). "Supported by the positive outcomes of combinational therapies involving MDM2 inhibitors, therapies targeting E3s upstream of PTEN may offer synergistic benefits in overcoming drug resistance and improving treatment outcomes in cancers with reduced PTEN expression." (PMID 40002221, 2025). "Compounds MJ2, MJ8, MJ15, and MJ19 had a stronger effect on the expression of the BCL2, MDM2, AIFM2, IL6, and IL8 genes in the healthy BEAS-2B cell line than in the cancerous HCT116 cell line, which may indicate their potential protective effect on normal cells with limited effect on cancer cells." (PMID 40725171, 2025). "Most recently, it was found that cancer cell lines that overexpress MDM2 show attenuated levels of γH2AX, a key mediator of DNA damage signaling, as a result of VP-16 treatment, while treatment with neocarzinostatin (a genotoxic anti-cancer drug) did not result in a noticeable difference in γH2AX." (PMID 38263255, 2024). "Surprisingly, even though the p53LCs could still bind to and be ubiquitinated by MDM2 in cancer cells, they were not degraded by this E3 ubiquitin ligase, as their half-lives were not reduced even in the presence of ectopic MDM2." (PMID 34918105, 2022). "We acknowledge that MX69 may have off-target effects, independent of MDM2, leading to further MM growth inhibition; future studies are warranted to fully elucidate such additional targets and possible other mechanisms underlying MX69′s anti-cancer properties." (PMID 35326742, 2022). "However, MDM2 inhibitor monotherapy may not be sufficient to achieve sustained clinical responses in cancer patients." (PMID 35008180, 2021).
cancer (continued). "What factors determine whether or not a cancer cell dies when MDM2 is inhibited?" (PMID 26079875, 2015). "Despite the fact that numerous MDM2 inhibitors and degraders have been assessed in clinical studies for various human cancers, no FDA-approved drug targeting MDM2 is presently available in the market." (PMID 40251828, 2025). "Surprisingly, MDM2 antagonists did not modulate VEGF expression in fibroblasts, suggesting a difference in the USP7 mode of action between cancer cells and fibroblasts." (PMID 38602256, 2024). "This review mainly discusses the relationship between MDM2 and cancer treatment resistance, especially TKI resistance, therefore, the relationship between MDM2 and other protein molecules will not be restated." (PMID 31440117, 2019). "Consistent with our findings, other studies also found no role for the same genes we tested in studies where populations enrolled were not enriched for positive cancer family history (for example, TNF-a or MDM2)." (PMID 30601841, 2019).
cancer (continued). "To test this we performed an in vitro kinase assay with the addition of bacterially purified MDM2 to MCF7 and T47D cancer cell extract from cells grown with or without overnight estrogen treatment." (PMID 28615518, 2017). "XIAP IRES increased colony formation of either SK-N-SH or SH-EP1 cells expressing MDM2 but not the SH-EP1 cells with MDM2 knockdown, suggesting that the effect of XIAP IRES on cancer cell growth is MDM2-dependent." (PMID 25888903, 2015). "MDM2 inhibitors have proven efficient in preclinical settings and, at present, agents such as AMG232 and RG7112 are clinically being explored in various cancer types, although not yet in uterine sarcomas." (PMID 26576131, 2015). "When comparing HLA-E positive with HLA-E negative cancer cells, analysis of the top 50 DEGs revealed several cell cycle-related genes that were highly expressed in HLA-E positive cancer cells, including CDKN1A, CDK4, and MDM2." (PMID 40959273, 2025). "A more reasonable strategy may be targeting both IL6 and MDM2 to decrease the pro-cancer consequences of IL6/GP130 signaling, both dependent and independent of MDM2 upregulation." (PMID 40961077, 2025). "Moreover, even if MDM2 rs3730485 and MDM4 rs4245739 were studied in several types of cancer, none of them included AML patients." (PMID 32492903, 2020). "However, in some other cancer cell types, in which FOXO1 does not regulate MDM2 transcription but instead activates CDKN1B transcription, FOXO1 may paradoxically act in a cancer-suppressing manner." (PMID 38519029, 2024). "However, even if side effects could be minimized, it is possible that MDM2 inhibition alone could be ineffective because inhibitors that target only MDM2 and not MDMX are ineffective against cancer cells that overexpress MDMX." (PMID 34386548, 2021). "In addition, multivariate analysis indicated that high MDM2 expression was a poor prognostic factor for PFS (HR = 5.61, 95% CI = 2.11-16.62, P = 0.0005) and OS (HR = 6.14, 95% CI = 1.85-24.32, P = 0.0028, independent of age and cancer stage." (PMID 27659536, 2016).